PES1 (pescadillo ribosomal biogenesis factor 1)
Description:
Component of the PeBoW complex, which is required for maturation of 28S and 5.8S ribosomal RNAs and formation of the 60S ribosome.
Synonyms: PES; NOP7
Tractability: Small molecule: a structure with a bound ligand is known. PROTAC: UniProt records ubiquitination sites on it; ubiquitination databases record sites on it; its protein half-life has been measured.
Gene: Protein-coding gene on chromosome 22 (30,576,625 to 30,607,083, reverse strand). Ensembl gene ENSG00000100029.
Subcellular location: Nucleus, nucleolus; Nucleus, nucleoplasm; Chromosome
Subcellular location (Human Protein Atlas): Mitotic chromosome; Nucleoli; Nucleoli rim; Nucleoplasm
Pathways (Reactome):
Metabolism of RNA: Major pathway of rRNA processing in the nucleolus and cytosol
Gene Ontology:
Molecular function: protein binding; RNA binding; ribonucleoprotein complex binding
Biological process: cell population proliferation; maturation of 5.8S rRNA from tricistronic rRNA transcript (SSU-rRNA, 5.8S rRNA, LSU-rRNA); maturation of LSU-rRNA from tricistronic rRNA transcript (SSU-rRNA, 5.8S rRNA, LSU-rRNA); regulation of cell cycle; rRNA processing; ribosomal large subunit biogenesis; ribosome biogenesis
Cellular component: chromosome; membrane; nucleolus; nucleoplasm; PeBoW complex; preribosome, large subunit precursor; nucleus
Genetic constraint (gnomAD): Loss-of-function variants: 29 observed, 72.7 expected, observed/expected ratio (o/e) 0.4, 90% interval 0.3 to 0.54. The upper end of that interval is the gene's LOEUF score, 0.54, which puts it in group 2 of 6, group 1 being the genes least tolerant of losing a copy. Missense variants: 646 observed, 777.85 expected, observed/expected ratio (o/e) 0.83, 90% interval 0.78 to 0.89. Synonymous variants: 280 observed, 307.04 expected, observed/expected ratio (o/e) 0.91, 90% interval 0.83 to 1.01.
Homologues: Orthologues: chimpanzee PES1 (99% identical), macaque PES1 (99% identical), pig PES1 (92% identical), guinea pig PES1 (90% identical), mouse Pes1 (90% identical), rat Pes1 (89% identical), dog PES1 (87% identical), guinea pig PES1 (86% identical), rabbit PES1 (80% identical), guinea pig PES1 (77% identical), zebrafish pes (73% identical), tropical clawed frog pes1 (72% identical), and 2 more.
Diseases named in the same sentence as PES1 in open-access papers:
PES1 is named in the same sentence as 48 diseases in open-access papers, as found by Europe PMC text mining. Sharing a sentence is not in itself a finding about the gene and the disease. The quoted sentences say what the papers report.
breast carcinoma (13 papers, 2012 to 2024). "Biological functions of components of the PeBoW complex, such as Pes1 and Bop1, have been implicated in multiple types of malignant tumor progression, including breast cancer, colon cancer, liver cancer, and melanoma." (PMID 34868955, 2021). "Furthermore, PES1 expression is found to be negatively associated with ERβ while positively correlated with ERα in breast cancer." (PMID 32448371, 2020). "Alternatively, it has been shown that PES1 promotes breast cancer by regulating the balance between ERα and ERβ." (PMID 36217758, 2023). "MTT analysis and colony formation analysis showed that PES1 knockdown inhibited the proliferation of breast cancer cells, and anchor-independent growth ability test results showed that PES1 knockdown also inhibited the tumorigenicity of breast cancer cells." (PMID 34976188, 2022). "In breast cancer cells, PES1 expression has been proved to be elevated; furthermore, proliferation and tumorigenicity were inhibited when PES1 levels were downregulated." (PMID 36361992, 2022). "PES1 mediates the balance between estrogen receptor (ER)β and ERα in tumor growth of estrogen-provoked breast cancer." (PMID 32448371, 2020). "Highly expressed PES1 is observed in various types of tumors, including breast cancer, gastric cancer, liver cancer, prostate cancer, and neuroblastoma." (PMID 31718704, 2019). "Clinical study has suggested that the expression of PES1 in breast cancer tissues (stage I-IV is much higher than that in normal breast tissues, while PES1 knockdown represses the growth and tumorgenesis of breast cancer cells." (PMID 27409667, 2016). "Previous research has shown that PES1 displays high expression in different tumors, including breast cancer." (PMID 27409667, 2016). "The role of PES1 SUMOylation in cell proliferation was investigated by determining the effect of PES1 SUMOylation on the proliferation of two breast cancer cell lines." (PMID 27409667, 2016). "Recently some other reports revealed PES1 overexpression in several other human cancers, including glioblastomas, breast cancer, and gastric cancer." (PMID 22860098, 2012). "PES1 expression was also significantly increased in breast cancer cells and tissues at both mRNA and protein levels, and was possibly controlled by estrogen." (PMID 22860098, 2012). "In an immunohistochemical analysis of breast cancer tissues, PES1 was detected in 88 of 92 (95.7%) cancer cases." (PMID 22860098, 2012). "The estrogen-induced SUMOylation of pescadillo ribosomal biogenesis factor 1 (PES1) stabilizes PES1 by inhibiting its ubiquitination, but mutation of K517R promotes the PES1 ubiquitin–proteasome pathway, thereby suppressing breast cancer cell proliferation and tumor growth." (PMID 39127633, 2024). "Furthermore, among breast cancer patients treated with tamoxifen, those with high PES1 expression tended to have a better prognosis." (PMID 34976188, 2022). "Immunohistochemical (IHC) staining results in 116 breast cancer tissues and 92 adjacent normal breast tissues showed that the expression of PES1 protein was positively correlated with the protein level of ERα and negatively correlated with the protein level of ERβ (P <0.0001)." (PMID 34976188, 2022). "PES1 promotes breast cancer development through multiple pathways." (PMID 33968766, 2021). "Multiple studies have mentioned that PES1 is overexpressed in various types of cancer tissues, including breast cancer, liver cancer, and gastric cancer, and that it participates in tumorigenesis by modulating cancer cell proliferation, apoptosis, and metabolism processes." (PMID 31718704, 2019). "PES1 promotes the growth of breast cancer cells by improving the stability of ERα." (PMID 27409667, 2016).
breast carcinoma (continued). "They found that PES1 enhances the stability of ERα while simultaneously targeting ERβ for proteasome degradation, thereby increasing the protein level of ERα and decreasing that of ERβ, which contributes to the occurrence and development of breast cancer and ovarian cancer." (PMID 30705367, 2019). "In PES1-overexpressed cells, PES1 could rescue ERα from degradation mediated by E2 and this may presumably prolong the transactivation activity of ERα in breast cancer cells." (PMID 27409667, 2016). "PES1 is a component of the nucleolar PeBoW complex (consisting of Pes1, Bop1 and WDR12) and is highly expressed in several kinds of cancers, including breast cancer." (PMID 33968766, 2021). "PES1 is also upregulated in several different carcinoma cell lines, such as the colon cancer cell line SW480 and human breast cancer cell line MCF-7." (PMID 27409667, 2016).
atherosclerosis (8 papers, 2019 to 2023). A disease characterized by the build-up of fatty material and calcium deposition in the arterial wall resulting in partial or complete occlusion of the arterial lumen. "In contrast, they posit that protection against atherosclerosis is associated with increased circANRIL, where circANRIL protects against over-proliferation by binding and impairing PES1 function to impede ribosomal RNA maturation." (PMID 35546161, 2022). "CircANRIL is believed to be a locus involved in atherosclerosis that promotes binding to pescadillo homolog 1 (PES1) and restrains 60S preribosomal assembly in VSMCs and macrophages, leading to cellular apoptosis and aggravation of atherosclerosis." (PMID 37896804, 2023). "For example, circANRIL, a circRNA located at 9p21, a locus known to be involved in atherosclerosis, can bind to pescadillo homolog 1 (PES1) and restrain 60S-preribosomal assembly in VSMCs and macrophages, which lead to cell apoptosis and atherosclerosis aggravation." (PMID 36712253, 2022). "Another example of this functional type is human lncRNA, called circANRIL, which binds the rRNA maturation factor PES1, thereby impairing ribosome biogenesis and preventing atherosclerosis by inducing apoptosis in a fraction of highly proliferative vascular cells." (PMID 31269716, 2019). "For example, circANRIL was bound to the essential 60S-preribosomal assembly factor pescadillo homolog 1 (PES1) and suppressed ribosome biogenesis in vascular smooth muscle cells and macrophages, resulting in nucleolar stress and cell death, which are key cellular events in atherosclerosis." (PMID 31973707, 2020). "Consequently, circ‐ANRIL promotes the apoptosis of different cells in the pathological process of atherosclerosis via interacting with Pes1; however, it is unknown whether circ‐ANRIL is atheroprotective in atherosclerosis." (PMID 33350091, 2021).
colon cancer (8 papers, 2012 to 2023). "In this study, we demonstrated that silencing of PES1 inhibited the proliferation and colony formation of colon cancer cells." (PMID 22860098, 2012). "We found that PES1 plays an oncogenic role in promoting proliferation of colon cancer cells and tumor formation in the nude mice model." (PMID 22860098, 2012). "Our study, in the first place, uncovers the oncogenic role of PES1 in colon cancer and elucidates the molecular mechanism directing PES1 expression." (PMID 22860098, 2012). "Recently, through somatic quantitative multiplex PCR for short fluorescent fragments (QMPSF) screening of 56 colon cancer tissues, only 5.4% (3/56) was identified to harbor increased copy number of PES1 gene." (PMID 22860098, 2012). "To examine the expression of PES1 in colon cancer tissues, we performed immunohistochemistical analysis of human colon cancer tissues and matched adjacent tissues with mAb 3B1." (PMID 22860098, 2012). "In this study, we generated three monoclonal antibodies recognizing PES1 with high specificity and sensitivity, with which PES1 expression in human colon cancer was analyzed immunohistochemically." (PMID 22860098, 2012). "Out of the 265 colon cancer tissues, 89 (33.6%) were positive for PES1 expression, whereas only 2.7% (7/265) of adjacent tissues showed PES1 staining." (PMID 22860098, 2012). "Our current study show that PES1 is overexpressed in colon cancers at both mRNA and protein levels, in comparison to the adjacent and normal colon tissues." (PMID 22860098, 2012). "Transcriptional factor c-Jun enhances PES1 expression by binding to the promoter region of PES1 and positive correlation between c-Jun and PES1 expression is evident in colon cancer cells and tissues." (PMID 22860098, 2012). "Our data revealed that transcriptional activation of PES1 by c-Jun is dependent on JNK in colon cancer cells." (PMID 22860098, 2012). "We were interested to find out the factor(s) controlling PES1 overexpression in colon cancer tissues." (PMID 22860098, 2012). "Silencing of PES1 in colon cancer cells resulted in decreased proliferation, reduced growth of xenografts, and cell cycle arrest in G1 phase, indicating PES1 functions as an oncogene." (PMID 22860098, 2012). "Likewise, colon cancer tissues displayed elevated expression of PES1, and in the absence of PES1, attenuated proliferation and tumor growth of colon cancer cell was observed, suggesting that downregulated PES1 functions as a tumor suppressor." (PMID 32448371, 2020). "In the present study, we demonstrated high expression of PES1 in colon cancer tissues." (PMID 22860098, 2012). "Moreover, we demonstrated a positive correlation between c-Jun and PES1 expression in colon cancer cells and colon cancer tissues." (PMID 22860098, 2012). "Previous studies have shown that overexpression of PES1 can lead to an increase in the percentage of 32D IRS-1 cell in the G2/M phase, whereas knockdown of PES1 can shorten the G2/M phase for colon cancer cells as well as repressing the growth of xenografts." (PMID 27409667, 2016). "PES1 is upregulated more in colon cancer tissues than in non-cancerous tissues, while down-regulation of PES1 in colon cancer cells can lead to cell cycle arrest at the G1 phase, as well as reduced proliferation and decreased growth of xenografts." (PMID 27409667, 2016). "Out of 265 colon cancer tissues, 89 (33.6%) showed positive PES1 expression, which was significantly higher than in non-cancerous tissues (P<0.001)." (PMID 22860098, 2012). "We then explored the mechanism by which PES1 expression is controlled in human colon cancers and demonstrated that c-Jun, but not JunB, JunD, c-Fos, or mutant c-Jun, positively regulated PES1 promoter transcription activity." (PMID 22860098, 2012). "The difference of PES1 expression between the colon cancer tissues and non-cancerous tissues was significant (P<0.001)." (PMID 22860098, 2012).
colon cancer (continued). "Preliminary data suggested that there were higher level of PES1 mRNA expression in colon cancer tissues than in match adjacent tissues, but no deregulated methylation was found in the promoter region of PES1 gene (data not shown)." (PMID 22860098, 2012). "Notably, as PES1 is up-regulated by CD44, c-Jun, and BRD4 in liver or colon cancer cells." (PMID 31718704, 2019). "Thus, increased expression of PES1 protein in colon cancers can not be fully explained by gene amplification." (PMID 22860098, 2012).
ovarian carcinoma (8 papers, 2019 to 2025). A malignant neoplasm originating from the surface ovarian epithelium. "For instance, PES1 has been shown to promote cell proliferation and is upregulated in neuroblastoma and ovarian cancer." (PMID 36217758, 2023). "Knockdown of PES1 downregulated cyclin D1 and upregulated cyclin-dependent kinase inhibitor p21WAF1 in ovarian cancer." (PMID 34976188, 2022). "Similar to PTC, PES1 has been shown to be highly expressed in ovarian cancer." (PMID 34976188, 2022). "Therefore, downregulated PES1 resulted in a delay in the development of ovarian cancer via activated ERβ but attenuated ERα, which further proposed PES1 as a therapeutic target for treatment of ovarian cancer, which was consistent with our findings." (PMID 32448371, 2020). "In addition, previous report showed that PES1 could regulate angiogenesis‐related gene expression in gastric and ovarian cancer." (PMID 37060584, 2023). "PES1, a BRCT domain-containing protein, has been shown to play a role in modulating the balance and ratio between ERα and ERβ protein, which is involved in the occurrence and development of breast and ovarian cancer." (PMID 30705367, 2019).
liver cancer (7 papers, 2019 to 2023). An epithelial or non-epithelial malignant neoplasm that arises from the liver. "People with high PES1 expression in liver cancer have a high risk of death." (PMID 34976188, 2022). "PES1 promoted the proliferation, migration, invasion and tumorigenesis of liver cancer cells 14, 16-18." (PMID 34976188, 2022). "CD44 regulates the expression of PES1 by regulating miR-105-5p and promotes the proliferation of liver cancer cells." (PMID 34712323, 2021). "Several studies have also shown that PES1 can be a prognostic biomarker for colon and liver cancer." (PMID 37076985, 2023).
neuroblastoma (7 papers, 2019 to 2025). Neuroblastoma (NB) is the most common solid, extracranial childhood tumor. "TUNEL assay results indicated that knockdown of PES1 inhibited the growth of neuroblastoma by inducing apoptosis." (PMID 34976188, 2022). "Here we found that neurospheres derived from neuroblastoma stem-like cells showed a homogeneous staining for several key nucleolar proteins, such as Nucleolin, Nucleophosmin-1, Glypican-2 and PES-1." (PMID 32737364, 2020). "Moreover, downregulation of PES1 has the potency to facilitate cell apoptosis and attenuate tumor growth in neuroblastoma, thus also acting as a marker to predict the treatment outcome of neuroblastoma." (PMID 32448371, 2020). "These groups went on to use these systems to investigate metabolic reprogramming in neuroblastoma and the roles of PRMT1 and PES1 in neuroblastoma cell survival." (PMID 40874091, 2025). "Among them, we focalized our attention on the proteins involved in neuroblastoma development, namely, Ubiquitin specific protease 7 (i.e., USP-7), Nuclear RNA export factor 1 (i.e., NXF1), and Pescadillo homolog (i.e., PES1)." (PMID 37298148, 2023).
colorectal cancer (5 papers, 2022 to 2025). A primary or metastatic malignant neoplasm that affects the colon or rectum. "PES1 transcription in colorectal cancer cells is also found to be mediated by the c-Jun NH2-terminal kinase (JNK) pathway." (PMID 37373047, 2023). "An MYC target gene, PES1, has been shown to have links with chemoresistance in colorectal cancer cells." (PMID 37373047, 2023). "Silencing of PES1 in this study inhibited the proliferation and growth of colorectal cancer cells in vitro and in vivo." (PMID 34976188, 2022). "Western blot analysis showed that PES1 is highly expressed in colorectal cancer." (PMID 34976188, 2022). "The results showed that in colorectal cancer, the expression of SLC35A2 was positively correlated with the expression of four MYC-associated genes, including MYC, Cyclin dependent kinase 4 (CDK4), Polo like kinase 1 (PLK1), and Pescadillo ribosomal biogenesis factor 1 (PES1)." (PMID 40303483, 2025). "Published results indicate that PPP2R5E, PES1, RRM2B, GLRX, and CRKL are important in the prognosis and development of colorectal cancer." (PMID 37895091, 2023). "In colorectal cancer, SNHG17 lncRNA inhibited PES1 ubiquitination and degradation via blocking the interaction of Trim23 and PES1." (PMID 35977942, 2022). "In addition, the ablation of PES1 impaired the ability of cells to repair DNA damage, reduced the rate of DNA repair and made cells more sensitive to chemotherapy drugs 59, which indicated that PES1 may be involved in regulating the sensitivity of colorectal cancer to chemotherapy." (PMID 34976188, 2022).
gastric cancer (4 papers, 2012 to 2022). A primary or metastatic malignant neoplasm involving the stomach. "PES1 was abnormally upregulated in adult human glioblastomas, head and neck squamous cell carcinomas (HNSCCs), and gastric cancer." (PMID 22860098, 2012). "PES1 has been reported to be highly expressed in gastric cancer and downregulation of PES1 suppresses the progression of gastric cancer, thus serving as a critical biomarker for the diagnosis of gastric cancer." (PMID 32448371, 2020).